ACSS2 (acyl-CoA synthetase short chain family member 2)
Diseases named in the same sentence as ACSS2 in open-access papers (continued):
Sharing a sentence is not in itself a finding about the gene and the disease.
cancer (continued). "However, within TME, cancer cells typically outcompete CD8+ T cells in acetate uptake and utilization due to their elevated expression of ACSS2 and MCT1 59,55." (PMID 41355959, 2026). "During lactation, breast tissue shows significantly higher expression of ACLY and ACSS2 genes than in the dry milk stage, and this is mirrored in cancer cells as opposed to normal cells." (PMID 41300803, 2025). "Acss2 and Acss2/HIF-2 signaling may have a particularly prominent role in growth and metastasis of cancers where extracellular acetate levels are elevated or where acetate is a primary substrate for growth." (PMID 36862715, 2023). "Even if the current evidence have widely proved that acetate is an essential nutrient for cancer growth, the therapeutical role of ACSS-2 is not fully explored." (PMID 36578540, 2022). "To compensate, cancer cells adopt different metabolic mechanisms, such as HIF-dependent stimulation of reductive glutamine metabolism, or acyl-CoA synthetase short-chain family member 2 (ACSS2)-mediated acetate metabolism for alternative sources of FA precursors." (PMID 34888248, 2021). "We observed an overall negative correlation between CD8+ T-cell fraction and ACSS2 expression in pan-cancer, except for GBM, where both components were negatively correlated based on all algorithms." (PMID 34206705, 2021). "The rescue of hypoxia-reduced ACSS1 and ACSS2 expression by acetate may indicate that ACSS1 and ACSS2 play an important role in cancer cells adapting to hypoxia." (PMID 27357947, 2016). "Thus, ACSS2/CBP/SIRT1/HIF-2 signaling links nutrient sensing and stress signaling with cancer growth and progression in mammals." (PMID 25689462, 2015). "Similarly, an ACSS2 inhibitor currently in clinical trials for a cancer indication, MTB-9655, also has no activity against CnAcs1." (PMID 39801522, 2025). "However, to our knowledge, there are currently no small molecule ACSS2 inhibitors that can cross the blood-brain barrier (BBB) for treating cancers in the brain." (PMID 38818373, 2024). "We also observed an increase in messenger RNA (mRNA) expression and the protein levels of acetate-synthesizing enzyme acetyl-CoA synthetase short-chain family member 2 (ACSS2, a nucleocytosolic enzyme) in acetate-treated cancer cells under acidosis but not under normal pH." (PMID 38429478, 2024). "However, this selective use of ACSS2-derived acetyl-CoA for histone acetylation does not occur in other cell types, such as cancer cell lines, due to a lack of nuclear or chromatin-localized ACSS2." (PMID 33917812, 2021). "This indicates that certain cancer cells may have an “acetate addiction” similar to the well-studied “glutamine addiction”, as the proliferation of normal cells is not affected by a lack of ACSS2." (PMID 33946927, 2021). "Inhibition of ACYL in CSCs has not shown significant effects due to the compensatory role of ACSS2, which replenishes acetyl-CoA in the absence of ACLY in cancer models." (PMID 39456967, 2024). "To investigate this, we generated cancer cell lines lacking both ACLY and ACSS2 [double knockout (DKO) cells]." (PMID 37134161, 2023). "In cancer cell lines lacking both ACLY and ACSS2, we show that a pool of cytosolic acetyl-CoA is maintained, that histone acetylation is active, and that both glucose and fatty acids can supply acetyl-CoA." (PMID 37134161, 2023). "Intriguingly, we show that in contrast to fibroblasts, cancer cells lacking both ACLY and ACSS2 [double knockout (DKO) cells] are viable, proliferate, contain a nuclear-cytosolic pool of acetyl-CoA, and sustain protein acetylation." (PMID 37134161, 2023).
infection (5 papers, 2011 to 2025). The state of being infected such as from the introduction of a foreign agent such as serum, vaccine, antigenic substance or organism. "To delineate the spatiotemporal dynamics of this metabolic–transcriptional axis, we tracked ACSS2 subcellular localization post infection." (PMID 40863614, 2025). "Strikingly, confocal microscopy revealed the robust nuclear translocation of ACSS2 upon oncoVV-AVL infection." (PMID 40863614, 2025).
kidney disease (4 papers, 2023 to 2024). "Using large-scale human genetics and genomics analysis, this work identifies ACSS2 as a kidney disease risk gene." (PMID 38357930, 2024). "In this study, we conducted a computational analysis of the chromosome 20 eGFR GWAS locus using expression, methylation QTL, and single-cell open chromatin data to prioritize Acyl-CoA synthetase short-chain family 2 (ACSS2) as a kidney disease risk gene." (PMID 38051585, 2023). "CRISPR-based locus deletion studies highlighted genetic variants that directly regulated ACSS2 levels, prioritizing ACSS2 as a likely kidney disease–causing gene." (PMID 38051585, 2023). "Here, we identify ACSS2 as a human kidney disease risk gene via the integration of human genetic (GWAS), kidney QTL (eQTL and mQTL), and human kidney single-cell expression (snATAC-Seq) data." (PMID 38051585, 2023). "Here, we used genetic mapping, kidney eQTL and mQTL, single-cell open chromatin information, and advanced statistical methods such as Bayesian colocalization, Mendelian randomization, and chromatin coaccessibility methods to prioritize ACSS2 as a kidney disease risk gene on chromosome 20." (PMID 38051585, 2023). "Collectively, our findings uncover that H3K9cr exerts a critical, previously unrecognized role in kidney fibrosis, where ACSS2 represents an attractive drug target to slow fibrotic kidney disease progression." (PMID 38615014, 2024). "Collectively, our findings uncover that H3K9 crotonylation plays a critical, previously unrecognized role in kidney fibrosis, where ACSS2 represents an attractive target for strategies that aim to slow fibrotic kidney disease progression." (PMID 38615014, 2024). "With genetic mapping and statistical analysis, the authors prioritized several genes in close proximity on chromosome 20, including acyl-CoA synthetase short-chain family 2 (ACSS2), as potential kidney disease driver genes." (PMID 38357930, 2024). "Here the author reveal that histone crotonylation (including H3K9cr) exert a role in kidney fibrosis, where ACSS2 represents a potential target to slow fibrotic kidney disease progression." (PMID 38615014, 2024). "ACSS2 gene and protein expression levels were lower in whole-kidney lysates from mice with kidney disease." (PMID 38051585, 2023). "While its role in renal diseases remains to be fully elucidated, in this study, for the first time, we demonstrated that ACSS2 was upregulated in the kidneys of individuals with DN and a diabetic mouse model." (PMID 37870960, 2023). "Genetic studies suggested a protective role for ACSS2, so we analyzed WT and Acss2–/– mice in an adenine-induced kidney disease model." (PMID 38051585, 2023). "Transcript levels of Col1a1, Col3a, and Fn1 were higher in the kidney disease models, but they were lower in Acss2–/– mice with kidney injury." (PMID 38051585, 2023). "We show that small molecules, such as FASNall, which targets FASN, and ACSS2i, which targets ACSS2, protected mice from developing kidney disease." (PMID 38051585, 2023). "We observed similar results in the adenine-induced kidney disease models with genetic deletion of Acss2 or Fasn, suggesting that NLRP3 inflammasome activation is associated with kidney disease development in these models." (PMID 38051585, 2023). "To investigate the role of ACSS2 in kidney disease, we generated mice with a genetic deletion of Acss2 using the CRISPR/Cas9 KO system." (PMID 38051585, 2023). "In summary, Acss2 -KO mice and kidney tubule cells showed protection from kidney disease." (PMID 38051585, 2023). "Gene prioritization analysis indicates that ACSS2 is a kidney disease gene." (PMID 38051585, 2023). "In summary, we observed changes associated with DNL in the mouse kidney disease model that were improved in the absence of ACSS2." (PMID 38051585, 2023). "In summary, our study identifies ACSS2 as a kidney disease gene." (PMID 38051585, 2023).
kidney disease (continued). "These investigations identify a role for ACSS2 in DNL and suggest that perturbation of DNL genes in kidney disease is protective." (PMID 38357930, 2024). "Our findings pinpoint ACSS2 as a critical kidney disease gene and reveal the role of DNL in kidney disease." (PMID 38051585, 2023). "Healthy controls and kidney disease samples showed strong expression of DNL genes, including ACSS2, NR1H3 (liver X receptor α [LXRA]), NR1H4 (farnesoid X receptor [FXR]), SREBF1, SCAP, PLIN2, PLIN5, ACACAB, ATP citrate lyase (ACLY), and FASN in PT cells and some other tubule cells." (PMID 38051585, 2023). "Furthermore, our work identifies ACSS2 and FASN as potential pharmacological targets for kidney disease." (PMID 38051585, 2023). "We propose that the crotonyl-CoA-producing enzyme, acyl-CoA synthetase short-chain family member 2 (ACSS2), could selectively regulate H3K9cr level and function, which represents an attractive drug target for strategies to slow fibrotic kidney disease progression." (PMID 38615014, 2024).
metabolic disorders (3 papers, 2015 to 2024). "In our study, ovarian HK1, HK2, PDHX and ACSS2 were repressed but FBP2 and ALDH1B1 were activated in DHT-treated rats, further complicating the metabolic disorders in those groups." (PMID 25887459, 2015).
neurodegenerative disease (1 paper, 2024). A disorder of the central nervous system characterized by gradual and progressive loss of neural tissue and neurologic function. "We thus suggest that ACSS2 may have far more protective roles in PPARs and other NRs related diseases including inflammation and neuropsychiatric disorders and neurodegenerative diseases and future work will be required to investigate ACSS2 function in these diseases." (PMID 38332049, 2024).
ACSS2 also shares sentences with these, for which no sentence is quoted: Alzheimer disease (3 papers); colorectal adenoma (2); fatty liver (2); multiple myeloma (2); neuroblastoma (2); acute kidney injury (1); acute myeloid leukemia (1); anemia (1); autoimmune polyendocrinopathy (1); bacterial infection (1); candidiasis (1); chronic kidney disease (1); clear cell renal cell carcinoma (1); cognitive decline (1); connective tissue disorder (1); cystic fibrosis (1); diabetic foot ulcer (1); endometrial cancer (1); injury (1); Insulin resistance (1); malaria (1); metastatic melanoma (1); nevus (1); oligodendroglioma (1); oral carcinomas (1); periodontitis (1); psychiatric disorder (1); skin cancer (1); skin cutaneous melanoma (1); tauopathy (1).
A further 3 diseases each share a sentence with ACSS2 in 1 paper.